SLC6A2 (solute carrier family 6 member 2)
Description:
Mediates sodium- and chloride-dependent transport of norepinephrine (also known as noradrenaline), the primary signaling neurotransmitter in the autonomic sympathetic nervous system. Is responsible for norepinephrine re-uptake and clearance from the synaptic cleft, thus playing a crucial role in norepinephrine inactivation and homeostasis (By similarity). Can also mediate sodium- and chloride-dependent transport of dopamine.
Synonyms: NET; NAT1; NET1; SLC6A5
Tractability: Small molecule: an approved drug acts on it; a structure with a bound ligand is known; a high-quality ligand is known; it belongs to a druggable protein family. Antibody: UniProt places it where antibodies can reach, with high confidence; its Gene Ontology location is reachable by antibodies, with high confidence; UniProt predicts a signal peptide or a membrane-spanning region. PROTAC: a small molecule that binds it is known.
Target class: SLC superfamily of solute carriers; SLC06 neurotransmitter transporter family; Electrochemical transporter; Transporter
Chemical probes: CHEMBL478834, PF-3409409
Safety:
Unwanted effects reported when the protein is acted on. In parentheses: how it was acted on, where the effect was seen, and who reports it.
constipation (Bowes et al. (2012): inhibition, cardiovascular system, central nervous system; Lynch et al. (2017): inhibition, acute dosing, nervous system, cardiovascular)
increased blood pressure (Bowes et al. (2012): inhibition, cardiovascular system, central nervous system; Lynch et al. (2017): inhibition, acute dosing, nervous system, cardiovascular)
increased heart rate (Lynch et al. (2017): inhibition, acute dosing, nervous system, cardiovascular; Bowes et al. (2012): inhibition, cardiovascular system, central nervous system)
abuse potential (inhibition; cardiovascular system, central nervous system; source: Bowes et al. (2012))
blurred vision (inhibition, acute dosing; nervous system, cardiovascular; source: Lynch et al. (2017))
congestive heart failure (inhibition; cardiovascular system; source: Urban et al. (2012))
decreased eating (inhibition, acute dosing; nervous system, cardiovascular; source: Lynch et al. (2017))
decreased locomotor activity (inhibition, acute dosing; nervous system, cardiovascular; source: Lynch et al. (2017))
decreased pain (inhibition, acute dosing; nervous system, cardiovascular; source: Lynch et al. (2017))
decreased pupillary reflex (inhibition, acute dosing; nervous system, cardiovascular; source: Lynch et al. (2017))
decreased salivation (inhibition, acute dosing; nervous system, cardiovascular; source: Lynch et al. (2017))
decreased sleep (inhibition, acute dosing; nervous system, cardiovascular; source: Lynch et al. (2017))
drug abuse/dependence (inhibition, acute dosing; nervous system, cardiovascular; source: Lynch et al. (2017))
hypertension (supine) (inhibition; cardiovascular system; source: Urban et al. (2012))
increased cardiac output (inhibition, acute dosing; nervous system, cardiovascular; source: Lynch et al. (2017))
increased locomotor activity (inhibition; cardiovascular system, central nervous system; source: Bowes et al. (2012))
increased QTc interval (inhibition, acute dosing; nervous system, cardiovascular; source: Lynch et al. (2017))
orthostatic hypotension (inhibition, acute dosing; nervous system, cardiovascular; source: Lynch et al. (2017))
sweating (inhibition, acute dosing; nervous system, cardiovascular; source: Lynch et al. (2017))
tachycardia (inhibition; cardiovascular system; source: Urban et al. (2012))
urinary hesitancy (inhibition, acute dosing; nervous system, cardiovascular; source: Lynch et al. (2017))
ventricular hypertrophy (inhibition, acute dosing; nervous system, cardiovascular; source: Lynch et al. (2017))
Gene: Protein-coding gene on chromosome 16 (55,655,988 to 55,707,645, forward strand). Ensembl gene ENSG00000103546.
Subcellular location: Cell membrane; Cell projection, axon; Synapse, synaptosome
Subcellular location (Human Protein Atlas): Cytosol; Mitochondria
Pathways (Reactome):
Disease: Defective SLC6A2 causes orthostatic intolerance (OI)
Transport of small molecules: SLC-mediated transport of neurotransmitters
Gene Ontology:
Molecular function: actin binding; dopamine:sodium symporter activity; monoamine transmembrane transporter activity; norepinephrine:sodium symporter activity; protein binding; neurotransmitter transmembrane transporter activity; alpha-tubulin binding; beta-tubulin binding; neurotransmitter:sodium symporter activity; sodium:chloride symporter activity
Biological process: norepinephrine uptake; amino acid transport; chemical synaptic transmission; dopamine uptake involved in synaptic transmission; neuron cellular homeostasis; neurotransmitter transport; sodium ion transmembrane transport; catecholamine uptake; chloride transmembrane transport; dopamine uptake; neurotransmitter reuptake; response to xenobiotic stimulus
Cellular component: plasma membrane; axon; membrane; neuronal cell body membrane; presynaptic membrane; cell surface; synapse; synaptic vesicle membrane
Genetic constraint (gnomAD): Loss-of-function variants: 25 observed, 67.26 expected, observed/expected ratio (o/e) 0.37, 90% interval 0.27 to 0.52. The upper end of that interval is the gene's LOEUF score, 0.52, which puts it in group 2 of 6, group 1 being the genes least tolerant of losing a copy. Missense variants: 564 observed, 826.99 expected, observed/expected ratio (o/e) 0.68, 90% interval 0.64 to 0.73. Synonymous variants: 358 observed, 352 expected, observed/expected ratio (o/e) 1.02, 90% interval 0.93 to 1.11.
Homologues: Orthologues: chimpanzee SLC6A2 (99% identical), macaque SLC6A2 (98% identical), mouse Slc6a2 (94% identical), rabbit SLC6A2 (94% identical), pig SLC6A2 (93% identical), rat Slc6a2 (93% identical), dog SLC6A2 (92% identical), guinea pig SLC6A2 (91% identical), tropical clawed frog slc6a2 (78% identical), zebrafish slc6a2 (73% identical). Paralogues in human: SLC6A3 (66% identical), SLC6A4 (49% identical), SLC6A6 (42% identical), SLC6A13 (42% identical), SLC6A5 (41% identical), SLC6A8 (41% identical), SLC6A12 (41% identical), SLC6A7 (40% identical), SLC6A11 (40% identical), SLC6A14 (40% identical), SLC6A9 (39% identical), and 6 more.